CCL28 (C-C motif chemokine ligand 28)
Diseases named in the same sentence as CCL28 in open-access papers (continued):
Sharing a sentence is not in itself a finding about the gene and the disease.
ulcerative colitis (3 papers, 2016 to 2024). An inflammatory bowel disease involving the mucosal surface of the large intestine and rectum. "Furthermore, increased CCL28 levels have been reported in the colonic mucosa and serum of ulcerative colitis patients, using immunohistochemistry and enzyme-linked immunosorbent assay, respectively." (PMID 33471872, 2021). "In humans, expression of CCL28 is increased in the inflamed colon of patients with ulcerative colitis." (PMID 27424033, 2016). "In the human gut, CCL28 is upregulated during inflammation of the gastric mucosa in Helicobacter pylori-infected patients and in the colon of patients with ulcerative colitis, a prominent form of inflammatory bowel disease." (PMID 39193987, 2024).
atopic dermatitis (2 papers, 2023 to 2025). "CCR10/CCL27–CCL28 help maintain homeostasis yet can drive pathology: inflammatory dermatoses (atopic dermatitis, psoriasis, allergic contact dermatitis) show abundant CCR10 T cells and elevated CCL27/CCL28, consistent with selective Th recruitment." (PMID 41050670, 2025). "Circulating levels of CCL28 and CXCL4 were reported to be markers of severity of atopic dermatitis and systemic sclerosis, respectively." (PMID 37353523, 2023).
cervical cancer (2 papers, 2023 to 2025). A primary or metastatic malignant neoplasm involving the cervix. "This study revealed that the presence of HPV16 and 18 oncogenes significantly alter the expression of CCL28, CXCL1, CXCL2, CXCL3, CXCL6, CXCL8, CXCL10, and CXCL11; overexpression of those chemokines was also confirmed in cervical cancer biopsies." (PMID 37893029, 2023).
eosinophilia (2 papers, 2015 to 2024). "CCL28 expression was increased in the lung of mice sensitized and challenged with cockroach antigen, and was associated with increased lung expression of CCR3 but not CCR10, and treatment with CCL28 antiserum reduces peribronchial eosinophilia and AHR." (PMID 26112287, 2015).
epilepsy (2 papers, 2015 to 2020). A brain disorder characterized by episodes of abnormally increased neuronal discharge resulting in transient episodes of sensory or motor neurological dysfunction, or psychic dysfunction. "In a mouse model of epilepsy, down-regulated expression of CCL28 in brain tissue was associated with neuronal loss." (PMID 31952511, 2020). "In a model of epilepsy, downregulated expression of CCL28 was associated with loss of neurons." (PMID 26834537, 2015).
gastrointestinal infection (2 papers, 2024). "Here, we discovered that the chemokine CCL28 significantly contributes to neutrophil accumulation and activation in the mucosa during gastrointestinal infection with Salmonella and lung infection with Acinetobacter." (PMID 39193987, 2024).
genital herpes (2 papers, 2021 to 2025). Herpes simplex infection of the genitals, most commonly caused by the herpes simplex-2 virus. "Accordingly, CXCL17(−/−) and CCL28(−/−) deficient mice lost protection against genital herpes." (PMID 41012114, 2025). "The CCL28 chemokine enhances protection against genital herpes by mobilizing antiviral effector memory cells into the infected vaginal mucosa." (PMID 41012114, 2025).
lung cancer (2 papers, 2024). A malignant neoplasm involving the lung. "Further, we isolated primary pericytes from lung cancer tissues to explore how CCL28 recruits pericytes in vitro." (PMID 39075504, 2024).
lymphoma (2 papers, 2024). A malignant (clonal) proliferation of B- lymphocytes or T- lymphocytes which involves the lymph nodes, bone marrow and/or extranodal sites. "The decreased expression of CCL28 and CXCL17, coupled with the increased expression of CCR1, may be linked to the progression of LGBLEL into lymphoma." (PMID 39451532, 2024). "RT-qPCR showed that, compared to the lymphoma group, the LGBLEL group had significantly higher expression of CCL28, CXCL17, HCK, GNB5, NRAS, and VAV2 (p = 0.001, <0.001, <0.001, <0.001, =0.020, <0.001, respectively) and lower expression of CCR1 (p = 0.002)." (PMID 39451532, 2024). "Compared to the lymphoma group, the protein quantitative analysis of the LGBLEL group exhibited significantly differentially expressed CCL28, CCR1, CXCL17, HCK, GNB5, NRAS, and VAV2 (p = 0.003, 0.011, 0.001, 0.024, 0.005, 0.019, and 0.031, respectively)." (PMID 39451532, 2024). "Compared to the lymphoma group, the LGBLEL group showed higher expression of CCL28, CXCL17, HCK, GNB5, NRAS, and VAV2 (p = 0.012, 0.005, 0.009, 0.011, 0.008, and 0.003, respectively) and lower expression of CCR1 (p = 0.014)." (PMID 39451532, 2024). "WB revealed that, compared to the lymphoma group, the LGBLEL group exhibited significantly higher expression of CCL28, CXCL17, HCK, GNB5, NRAS, and VAV2 (p = 0.012, 0.005, 0.009, 0.011, 0.008, and 0.003, respectively) and lower expression of CCR1 (p = 0.014)." (PMID 39451532, 2024). "Compared to the lymphoma group, the LGBLEL group exhibited higher expression levels of CCL28, CXCL17, HCK, GNB5, NRAS, and VAV2 (p = 0.001, <0.001, <0.001, <0.001, 0.020, and <0.001, respectively) and lower expression of CCR1 (p = 0.002)." (PMID 39451532, 2024). "Our findings showed that CCL28 was highly expressed in the acinar and the lymphocyte infiltration regions of LGBLEL but absent in the lymphoma group." (PMID 39451532, 2024).
mastitis (2 papers, 2015 to 2021). Inflammation of breast tissue during lactation or postpartum due to an obstructed duct or infection. "Because of its relation with antimicrobial activity, CCL28 can play an important role in mastitis control and thus, indirectly influencing milk production." (PMID 34828436, 2021). "Bovine CCL28 was shown to mediate cellular chemotaxis via the CCR10 chemokine receptor and exhibited antimicrobial activity against a variety of bovine mastitis causing organisms." (PMID 26359669, 2015). "In many cases the levels of bCCL28 in bovine milk exceeded those required for significant antimicrobial activity in vitro, suggesting CCL28 may contribute to mastitis prevention and/or recovery." (PMID 26359669, 2015). "Somatic cell counts (high somatic cell counts are indicative of mastitis) were not linearly correlated with CCL28 levels (R2 = 0.007; Pearson’s correlation = 0.10, p = 0.39)." (PMID 26359669, 2015).
Salmonella Infections (2 papers, 2023 to 2024). Infections with bacteria of the genus SALMONELLA. "CCL28 was also shown to be notably involved in the immune response to mucosal pathogens by regulating neutrophil recruitment and activation, and CCL28 knockout mice were highly susceptible to Salmonella infection in the gut." (PMID 36713846, 2023). "However, it is still possible that CCL28 modulates B and T cell responses in chronic model of Salmonella infection, which could be explored in future studies using attenuated Salmonella strains, or mice genetically more resistant to Salmonella because they express a functional Nramp1." (PMID 39193987, 2024). "CCL28 stimulation of bone marrow neutrophils in vitro increased their antimicrobial activity and ROS production during Salmonella infection, which was reverted by blocking CCR3 but not CCR10." (PMID 39193987, 2024).
stomach cancer (2 papers, 2021 to 2023). "CCL28, a crucial mediator between oncogenic β-catenin signaling and the stomach tumor microenvironment, is shown to have an integral part of cancer development by either facilitating cancer cell proliferation or metastasis or by forming the tumor immune microenvironment." (PMID 34337075, 2021).
Stroke (2 papers, 2022). Sudden impairment of blood flow to a part of the brain due to occlusion or rupture of an artery to the brain. "Gut-derived Treg cells have been confirmed to feature in the prognosis of stroke, and studies have confirmed that programmed death protein 1 (PD-1) and CC-chemokine ligand 28 (CCL28) regulate Treg cells." (PMID 36440294, 2022).
abortion (1 paper, 2019). the ending of pregnancy by removing a fetus or embryo before it can survive outside the uterus. "CCL28 has been found to induce apoptosis in decidual stromal cells, and a higher expression of the receptors of CCL28 (CCR3, CCR10), in these cell populations in spontaneous abortion is displayed prior to a pro-inflammatory stimulation." (PMID 30755659, 2019).
Acinetobacter infection (1 paper, 2024). "A reduction of neutrophil accumulation was also observed in the BAL and lung of Ccl28−/− mice during Acinetobacter infection, with neutrophils recruited to the lung harboring surface CCR3 and CCR10." (PMID 39193987, 2024).
acute kidney injury (1 paper, 2024). Sudden and sustained deterioration of the kidney function characterized by decreased glomerular filtration rate, increased serum creatinine or oliguria. "In the I/R-induced renal injury model of male mice, researchers found that knocking down ALKBH5 increased the expression of CCL28 through m6A modification, regulated the downstream CCL28/Treg/inflammatory cell axis, thereby alleviating I/R-induced acute kidney injury and renal fibrosis." (PMID 39220683, 2024).
acute myeloid leukemia (1 paper, 2016). Acute myeloid leukemia (AML) is a group of neoplasms arising from precursor cells committed to the myeloid cell-line differentiation. "Acute myeloid leukemia is a heterogeneous and aggressive disease, and in a previous study of another smaller patient population, we observed that exogenous CCL28 could modulate cytokine-dependent AML cell proliferation for a minority of patients." (PMID 27252705, 2016).
adenocarcinoma of esophagus (1 paper, 2018). "The latest gene, CCL28 demonstrated significant linkage in the progression from BE to the adenocarcinoma of esophagus." (PMID 30774811, 2018).
allergic asthma (1 paper, 2015). A asthma with a basis in a pathological type I hypersensitivity reaction. "Potential involvement of the CCR10/CCL28 axis was recently reported in murine models of allergic asthma." (PMID 26112287, 2015).
atrophic gastritis (1 paper, 2020). "In superficial gastritis and atrophic gastritis, the expression levels of chemokines/interleukins are relatively the same (IL14, CXCL14, and CCL28 had higher expression levels; IL3, CCL26, IL31, etc., had lower expression levels), only with a slight difference." (PMID 33426088, 2020).
Autoimmunity (1 paper, 2019). The occurrence of an immune reaction against the organism's own cells or tissues. "CCL28 is suggested to have anti-inflammatory properties by limiting autoimmunity and inflammation at these sites." (PMID 30755659, 2019).
biliary tract cancer (1 paper, 2024). "In biliary tract cancers, elevated serum CCL23 predicted a dismal prognosis, and PEA-measured high plasma CCL28 levels implied worse survival in epithelial ovarian cancers." (PMID 38594742, 2024).
Bovine mastitis (1 paper, 2015). INFLAMMATION of the UDDER in cows. "In an effort to better understand the potential role of CCL28 in preventing/combating bovine mastitis, we cloned and expressed bCCL28 and tested the function of this protein in both chemotaxis and antimicrobial assays." (PMID 26359669, 2015).
Candida infection (1 paper, 2012). "Of the chemoattractant mediators, several chemokines (Ccl25, Ccl27, Ccl28) and chemokine receptors (Ccr9, Ccr10, Cxcr5, Cxcr6, Cxcr7) associated with adaptive immunity were not induced after Candida infection." (PMID 22916017, 2012).
celiac disease (1 paper, 2016). An autoimmune genetic disorder with an unknown pattern of inheritance that primarily affects the digestive tract. "The chemokine CCL28 (MEC) preferentially attracts IgA+ cells that are numerous in the LP of Cd11ccreIl10rafl/fl mice as well as celiac disease patients." (PMID 27027442, 2016).
Cerebral ischemia (1 paper, 2019). Restriction of arterial blood supply to the brain associated with insufficient oxygenation to support the metabolic requirements of the tissue. "CCL28 was increased in superficial CLNs but not in ILNs, and the blockade of VEGFR3 tyrosine kinase with MAZ51 treatment significantly reduced CCL28 in superficial CLNs after cerebral ischemia." (PMID 31757960, 2019). "In addition, analysis of the full micro-array dataset revealed that CCL28 was the most significantly altered chemokine in the CLN after cerebral ischemia." (PMID 31757960, 2019).
complication (1 paper, 2024). Any disease or disorder that occurs during the course of, or because of, another disease, treatment, or procedure. "Our findings demonstrated that genetically predicted higher levels of IL-12B and LIF likely increased the risk of T1D with renal complications, whereas higher levels of ARTN, CCL28, and S100A12 were related to a decreased risk." (PMID 39040677, 2024).
dementia (1 paper, 2023). Loss of intellectual abilities interfering with an individual's social and occupational functions. "Interestingly, this panel of proteins, except RSPO1 and CCL28, were also identified using the machine learning multivariate model (diagnostic Panel B) that discriminated dementia from MCI, with an AUC = 0.87." (PMID 37175824, 2023).
diabetic nephropathy (1 paper, 2024). "In the context of diabetic nephropathy, we postulated that ARTN may be instrumental in supporting the survival and repair of injured neurons or other cell types, while CCL28 is likely implicated in modulating inflammation, immune responses, and tissue repair mechanisms." (PMID 39040677, 2024).
E. coli infection (1 paper, 2016). "Taken together, the upregulated expression of CCL28 and CCR10 in the intestinal mucosa following consumption of high-dose BLS-mix is partly involved in clearance of the pathogen, but also is associated with intestinal inflammation during E. coli infection." (PMID 27424033, 2016).
intestinal cancer (1 paper, 2023). "Cochrane’s Q test did not provide evidence of heterogeneity between CCL14 (p = 0.768, p = 0.808), CCL22 (p = 0.502), CCL28 (p = 0.175), CXCL12 (p = 0.530) and CXCL14 (p = 0.534) and intestinal cancer." (PMID 38075694, 2023).
latent infection (1 paper, 2021). "Compared with CCL19, here we found that CCL28 has an advantage in inducing long-lasting serum neutralizing Abs postchallenge and more potent systemic Abs, which may be the dominant reason for the rapid removal of HSV-2 after challenge and the reduction in establishing latent infection." (PMID 33910988, 2021).
lipid metabolism disorders (1 paper, 2024). "Overexpression of ALKBH5 increases FABP5 expression in a m6A-IGF2BP2 dependent manner, leading to lipid metabolism disorders.The research report that inhibition of ALKBH5 could promote m6A modification of CCL28 mRNA and increase its stability." (PMID 38918701, 2024).
metabolic syndrome (1 paper, 2021). A cluster of metabolic risk factors for CARDIOVASCULAR DISEASES and TYPE 2 DIABETES MELLITUS. "CCL28 has only recently and for the first time been inversely associated with the metabolic syndrome in Japanese adults also using PEA proteomics." (PMID 34151535, 2021).
metastatic cancer (1 paper, 2024). A carcinoma which has spread from the original site of growth to another anatomic site. "We compared the expression differences between metastatic cancer and primary cancer and found that, apart from a significant downregulation of CXCL14 and CCL28, as well as a significant upregulation of CXCL12 and CCL2, the expression levels of most chemokines did not achieve a twofold change." (PMID 39409185, 2024).
metastatic tumors (1 paper, 2011). "Conversely, CCL28 and VEGF-A were both amplified and had higher gene expression in the primary versus metastatic tumors." (PMID 22194851, 2011).
myeloma (1 paper, 2016). "None of the cell lines migrated in response to the CCL28 concentrations tested and both chemokines had no impact on myeloma cell proliferation." (PMID 27732933, 2016). "Whereas CCL27 rescued myeloma cells from drug-treatment, addition of CCL28 had no impact on cell survival in both assays." (PMID 27732933, 2016).
neuroendocrine carcinoma (1 paper, 2024). A malignant neuroendocrine neoplasm composed of cells containing secretory granules that stain positive for NSE and chromogranin. "On the other hand, some chemokines such as CCL28 and CCL14 were downregulated in high-grade neuroendocrine carcinoma compared to normal tissue." (PMID 39097562, 2024).
oral cancer (1 paper, 2024). "More detailed analyses of changes in CCL28 expression caused by diseases such as human oral cancer will be necessary to strengthen the possibility that CCL28 assists in diagnosing human diseases." (PMID 38534417, 2024).
osteosarcoma (1 paper, 2022). A usually aggressive malignant bone-forming mesenchymal neoplasm, predominantly affecting adolescents and young adults. "The result indicated that CCL28, KLF2 and TNFSF18 did not significantly affect cell apoptosis, while the knockdown of HMGB1 and TLR4 significantly increased the proportion of apoptotic of osteosarcoma cells." (PMID 36204682, 2022).
Parkinson disease (1 paper, 2020). A progressive degenerative disorder of the central nervous system characterized by loss of dopamine producing neurons in the substantia nigra and the presence of Lewy bodies in the substantia nigra and locus coeruleus. "Another molecular biomarker that has proven to be important in detecting neuroinflammation and to have diagnostic value for Parkinson’s disease is CCL28 (Mucosae-associated epithelial chemokine; MEC)." (PMID 33182554, 2020).
pneumonia (1 paper, 2024). An acute, acute and chronic, or chronic inflammation focally or diffusely affecting the lung parenchyma, caused by an infection in one or both of the lungs (by bacteria, viruses, fungi, or mycoplasma.). "Therefore, CCL28 contributes to lung inflammation and neutrophil accumulation during Ab pneumonia, similar to its role in STm gut infection." (PMID 39193987, 2024).
primary Sjögren’s syndrome (1 paper, 2020). "CCL28 is not detected in salivary glands of primary Sjögren’s syndrome patients." (PMID 32371984, 2020).
pulmonary fibrosis (1 paper, 2023). Chronic progressive interstitial lung disorder characterized by the replacement of the lung tissue by connective tissue, leading to progressive dyspnea, respiratory failure, or right heart failure. "Taken together, these findings highlight a role for the signaling pair CCL28/CCR10 in promoting pulmonary fibrosis and enables us to hypothesize that the CCL28/CCR10 axis could also drive fibrosis in SSc." (PMID 38139427, 2023).
Respiratory tract infection (1 paper, 2015). An infection of the upper or lower respiratory tract. "During respiratory tract infections, in addition to its chemokine role in attracting immune cells expressing CCR10, CCL28 likely provides additional mucosal immunity by exerting an antimicrobial effect against pathogens." (PMID 26112287, 2015).
salivary gland tumors (1 paper, 2025). "In patients with salivary gland tumors (WT and PA), various chemokines have been determined, including CCL28, CXCL10, CXCL12, CCL18, and CXCL1, as well as pro-inflammatory cytokines such as IL-1β, IL-6, IL-4, IL-17, and IL-33." (PMID 40807046, 2025).
Sepsis (1 paper, 2024). Sepsis is defined as life-threatening organ dysfunction caused by a dysregulated host response to infection. "CCL19 (OR = 1.810, 95% CI = 1.018 ~ 3.219, P = 0.043) and C-C motif chemokine 28 levels (CCL28) (OR = 3.791, 95% CI = 1.215 ~ 11.825, P = 0.022) significantly increased risk of sepsis (28-day mortality in critical care units)." (PMID 39176264, 2024). "According to the MR analysis, we found that C-C motif chemokine 19 (CCL19), C-C motif chemokine 28 (CCL28), TNF-related apoptosis-inducing ligand (TRAIL), and vascular endothelial growth factor A (VEGF-A) levels were associated with an increased risk of sepsis-related outcomes." (PMID 39176264, 2024). "However, research on the relationship between CCL19 and CCL28 and sepsis is currently limited." (PMID 39176264, 2024).